COMP (cartilage oligomeric matrix protein)
Diseases named in the same sentence as COMP in open-access papers (continued):
Sharing a sentence is not in itself a finding about the gene and the disease.
invasive breast carcinoma (2 papers, 2006 to 2011). A carcinoma that infiltrates the breast parenchyma. "Stromal reaction to invasive breast carcinoma was associated with increased expression of genes encoding ECM components, proteolytic enzymes and adhesion receptors, including COL11A1, COL10A1, COMP, MMP11, FN1 and MFAP2, consistent with the abundant stromal remodeling observed by histology." (PMID 21611158, 2011). "Similarly to POSTN, COMP and IL8 could be clearly detected in the epithelial cells of 21% and 13.9% invasive breast carcinomas, respectively." (PMID 17014703, 2006).
leukaemia (2 papers, 2023 to 2024). "HDAC1 increases activity of leukemia/lymphoma-related factors and suppresses COMP transcription in C3H10T1/2 cells." (PMID 37681413, 2023). "In addition, we also found some leukaemia‐specific proteins, oncogenes (COL2A1, CLIP1, NUMA1 and GALK1), and stem cell‐regulated proteins (ACAN, VCAN, COMP and PRDX6)." (PMID 38499475, 2024).
Marfan syndrome (2 papers, 2012 to 2025). A disorder of the connective tissue. "•The decrease of plasma COMP is a common pathology for nonfamilial TAD and Marfan syndrome." (PMID 40680508, 2025).
multiple epiphyseal dysplasia type 1 (2 papers, 2017 to 2022). Multiple epiphyseal dysplasia type 1 (MED 1) is a form of multiple epiphyseal dysplasia that is characterized by normal or mild short stature, pain in the hips and/or knees, progressive deformity of extremities and early-onset osteoarthrosis. "In contrast to COMP knockout mice, which showed normal skeletal development, dominant missense mutations of human COMP result in autosomal dominant pseudoachondroplasia and multiple epiphyseal dysplasia type 1." (PMID 29262782, 2017). "Mutations in the COMP gene can disrupt cartilage and bone formation, leading to rare skeleton diseases pseudoachondroplasia (PSACH) and multiple epiphyseal dysplasia type 1 (MED1)." (PMID 36012514, 2022).
non-small cell lung carcinoma (2 papers, 2025). A group of at least three distinct histological types of lung cancer, including non-small cell squamous cell carcinoma, adenocarcinoma, and large cell carcinoma. "COMP expression provides radiation resistance in non-small cell lung cancer (NSCLC)." (PMID 41009743, 2025). "Cartilage oligomeric matrix protein (COMP) is an extracellular matrix protein that binds to the cell surface and activates the PI3k/AKT pathway; thus it is possible COMP expression may be directly associated with radiation resistance in non-small cell lung cancer (NSCLC)." (PMID 40141111, 2025).
osteophytes (2 papers, 2019 to 2025). "The increased COMP and PIIANP levels for those with osteophytes at baseline support the role of ECM turnover in this process, though subsequent adjustment and correction made these differences non-significant." (PMID 41194279, 2025). "COMP had an AUROC of 0.604 (0.543,0.664) for new cases of JSN, COMP, IL-1β and leptin had an AUROC 0.586 (0.524,0.646) for new osteophytes, and TNF-α, IL-1β and adiponectin had an AUROC 0.590 (0.520,0.659) for new sclerosis." (PMID 41194279, 2025).
osteoporosis (2 papers, 2005 to 2023). A condition of reduced bone mass, with decreased cortical thickness and a decrease in the number and size of the trabeculae of cancellous bone (but normal chemical composition), resulting in increased fracture incidence. "Importantly, BMSCs isolated from patients with osteoporosis showed a decrease in histone H3K18la lactylation and the expression of the target genes COL1A2, COMP, ENPP1, and TCF7L2." (PMID 37752768, 2023). "qPCR analysis of the target genes of H3K18la lactylation indicated that the expression of the osteogenic genes COL1A2, COMP, ENPP1, and TCF7L2 was decreased in BMSCs isolated from patients with osteoporosis compared with that in BMSCs from patients without osteoporosis." (PMID 37752768, 2023).
pulmonary arterial hypertension (2 papers, 2023 to 2025). Pulmonary arterial hypertension (PAH) is a group of diseases characterized by mean pulmonary artery pressure >20 mmHg and elevated pulmonary arterial resistance leading to right heart failure. "In the SuHx animal model, which exhibits a more severe form of pulmonary hypertension, there is an activation of MMP9-mediated cleavage of COMP and subsequently loss of its stabilization of BMPR2." (PMID 38001814, 2023).
Sepsis (2 papers, 2020 to 2025). Sepsis is defined as life-threatening organ dysfunction caused by a dysregulated host response to infection. "This was supported by a previous investigation in COMP release into digital sheath synovial fluid where total COMP concentration was greatly increased by the presence of sepsis which is highly inflammatory." (PMID 32245107, 2020).
serous ovarian carcinoma (2 papers, 2024). "Interestingly, COMP was the most upregulated protein when the stroma protein content of high-grade serous ovarian carcinoma was characterized with proteomic analysis." (PMID 38563861, 2024). "Interestingly, COMP has been shown to be the most overexpressed protein in the stroma of omental metastases of high-grade serous ovarian cancer patients, and higher in the stroma of omental biopsies than in tumor cells." (PMID 38615020, 2024). "In addition, the overall expression of COMP in serous ovarian cancer, derived from the online Kaplan–Meier plotter database, indicated a correlation of high COMP expression with shorter OS and progression-free survival." (PMID 38615020, 2024).
Stroke (2 papers, 2020 to 2023). Sudden impairment of blood flow to a part of the brain due to occlusion or rupture of an artery to the brain. "Again, our study adds to the existing literature by reporting on the relationship between COMP levels and cognitive function post-stroke." (PMID 37280551, 2023).
tendonitis (2 papers, 2013). "Therefore, the rise in COMP serum concentrations during the marathon may be indicative of the severe physical strain on joint structure, but may also be associated with tendonitis, synovitis or meniscus injury." (PMID 23519606, 2013). "This study reported an increase in the expression of the gene cartilage oligomeric matrix protein (COMP) after tendonitis therapy with mononuclear cells derived from adipose tissue." (PMID 23876512, 2013).
Venous malformation (2 papers, 2012 to 2016). A vascular malformation resulting from a developmental error of venous tissue composed of dysmorphic channels lined by flattened endothelium and exhibiting slow turnover. "For example, COMP-Ang-1 is more potent than native Ang-1 in phosphorylating Tie2 and also induces larger vessels and increases blood flow, mimicking the activating mutation of Tie2 found in inherited venous malformations." (PMID 27454431, 2016). "Biological MAT.Ang-1 units consist of trimers and tetramers rather than more active pentamers, and hence - compared with COMP.Ang-1 - side effects such as venous malformations are less likely to occur when administered systemically." (PMID 23036162, 2012).
abdominal aortic aneurysm (1 paper, 2021). Enlargement and ballooning of the vessel that supplies arterial blood to the abdomen, pelvis and legs. "Here, we show that an extracellular matrix protein, cartilage oligomeric matrix protein (COMP), acts as an endogenous allosteric biased modulator of the AT1 receptor and its deficiency is clinically associated with abdominal aortic aneurysm (AAA) development." (PMID 33510386, 2021).
acute coronary syndrome (1 paper, 2023). Signs and symptoms related to acute ischemia of the myocardium secondary to coronary artery disease. "Interestingly, in non-RA patients with acute coronary syndromes, serum levels of COMP were positively correlated with the risk of subsequent major adverse cardiovascular events." (PMID 38037148, 2023).
Atherosclerotic lesion (1 paper, 2023). A lesion associated with atherosclerosis, a multifactorial and multipart progressive disease manifested by the focal development within the arterial wall of lesions, that ranges from the development of a fatty streak, plaque progression, and plaque disruption. "As a metalloproteinase, ADAMST7 is responsible for the degradation of cartilage oligomeric matrix protein (COMP), also known as thrombospondin-5 (TSP5), which is a component of vascular ECM and was also found to be present in atherosclerotic lesions." (PMID 36833435, 2023).
carotid atherosclerosis (1 paper, 2023). A thickening and loss of elasticity of the walls of carotid arteries that occur with formation of atherosclerotic plaques. "A previous study reported cartilage oligomeric matrix protein (COMP) to be positively associated with worse plaque burden and plaques that were symptomatic in carotid atherosclerosis." (PMID 37280551, 2023).
cerebral edema (1 paper, 2014). "Cerebral edema was significantly suppressed in the COMP-Ang1 group compared to the COMP group (17.8% vs. 35.9%; p = 0.038)." (PMID 24896569, 2014). "We demonstrated that COMP-Ang1 protein could suppress the hemorrhagic transformation as well as cerebral edema after tPA treatment." (PMID 24896569, 2014). "Because administering COMP-Ang1 protein may result in the suppression of hemorrhagic transformation and cerebral edema, Ang1 can be considered to be a promising target molecule for vasoprotective treatment to prevent the BBB damage that accompanies tPA treatment." (PMID 24896569, 2014).
chondromalacia patellae (1 paper, 2025). Familial chondromalacia patellae is an inherited bone disorder described in 5 families in 1963 and is characterized by localized patellar pain and male-to-male transmission. "Subjects with chondromalacia patellae exhibited greater s-COMP levels compared to controls." (PMID 40149737, 2025).
chordoma (1 paper, 2022). Chordomas are rare malignant tumors arising from embryonic remnants of the notochord in axial skeleton. "As expected, stroma-rich chordomas showed elevated expression of cartilage-associated genes, including COMP, MATN3, and COL11A226,27." (PMID 36192442, 2022).
clubfoot (1 paper, 2023). The most common congenital deformation of the foot, occurring in 1 of 1,000 live births. "Mutations in genes encoding the ECM proteins COL9A1, COL9A2, COL9A3, COMP and MATN3, as well as the transmembrane glycoprotein involved in matrix organization, SLC26A2, have been associated with clubfoot." (PMID 37964341, 2023).
collagenopathy (1 paper, 2022). "We compared the height Z score of collagenopathy patients with other different-causing gene mutations and found that the ACAN mutation resulted in milder short stature than the collagen gene mutation (p = .021), while the COMP mutation was the most severe (p = .009)." (PMID 35250876, 2022).
coronary artery calcification (1 paper, 2025). Calcification of the coronary artery, used as a measure of coronary atherosclerosis, a risk factor for myocardial infarction. "Another study reported higher circulating levels of COMP in patients with CAD and found a positive correlation between COMP levels and coronary artery calcium scores, advocating its potential as a biomarker for coronary artery calcification." (PMID 41300494, 2025).
crystal arthritis (1 paper, 2023). "Furthermore, colchicine is known to reduce the formation of IL-1 levels in crystal arthritis, and IL-1 has been shown to be correlated with serum COMP levels in OA." (PMID 36224305, 2023).
cystic fibrosis (1 paper, 2018). Autosomal recessive disorder caused by pathogenic variants in the CFTR gene (cystic fibrosis transmembrane conductance regulator), which encodes a chloride and bicarbonate channel expressed in epithelial cells, and follow the diagnosis criteria. "Fluoxetine, methyldopa and sulfadiazine can inactivate cystic fibrosis trans-membrane conductance regulator and sequentially down-regulate the expression of Collagen, THBS, COMP and PRELP." (PMID 30115125, 2018).
diabetic neuropathy (1 paper, 2012). A chronic, pathological complication associated with diabetes mellitus, where nerve damages are incurred due to diabetic microvascular injury involving small blood vessels that supply these nerves, resulting in peripheral and/or autonomic nerve dysfunction. "In conlusion, COMP-Ang-1 recovers molecular biomarkers of neuropathy, promotes angiogenesis and suppresses inflammation in sciatic nerves of ob/ob mice suggesting COMP-Ang-1 as novel treatment option to improve morphologic and protein expression changes associated with diabetic neuropathy." (PMID 22412941, 2012). "COMP-Ang-1 recovers molecular biomarkers of neuropathy, promotes angiogenesis and suppresses inflammation in sciatic nerves of ob/ob mice suggesting COMP-Ang-1 as novel treatment option to improve morphologic and protein expression changes associated with diabetic neuropathy." (PMID 22412941, 2012).
dilatation (1 paper, 2018). "The degradation of COMP in cardiac fibroblasts could result in a decrease in type I collagen secretion that changes ECM components and promotes ventricular dilatation." (PMID 29523183, 2018).
embryonal rhabdomyosarcoma (1 paper, 2025). A poorly circumscribed morphologic variant of rhabdomyosarcoma. "Interestingly, despite prior studies reporting elevated COMP expression in various cancers, our results revealed a significant downregulation of COMP in embryonal rhabdomyosarcoma." (PMID 40710368, 2025).
endometrial cancer (1 paper, 2021). Primary or metastatic malignant neoplasm involving the endometrium (mucous membrane that lines the endometrial cavity). "Thus, the finding in our study that COMP and DMBT1 expression is associated with survival in endometrial cancer is supported by previous studies reporting the same for other cancers." (PMID 33540589, 2021).
epithelial ovarian tumor (1 paper, 2024). "To study the association of COMP expression in cancer cells and stroma with clinicopathological features of ovarian tumor patients, we analyzed an epithelial ovarian tumor cohort by immunohistochemical analysis." (PMID 38615020, 2024).
esophageal adenocarcinoma (1 paper, 2024). A malignant tumor with glandular differentiation arising predominantly from Barrett mucosa in the lower third of the esophagus. "In conclusion, this study provides the initial observation of COMP expression in tumors samples derived from patients with gastric and esophageal adenocarcinoma using immunohistochemistry staining." (PMID 38563861, 2024). "Herein, the expression of COMP was investigated in gastric and esophageal adenocarcinoma with particular reference to its the relationship with the immune microenvironment." (PMID 38563861, 2024). "In contrast, patients with esophageal adenocarcinoma had fewer infiltrating CD8+ T-cells (p = 0.042) when COMP was expressed in the stroma." (PMID 38563861, 2024). "The current study demonstrated that COMP is expressed in the tumors of patients with gastric or esophageal adenocarcinoma." (PMID 38563861, 2024). "Expression of COMP in gastric and esophageal adenocarcinoma was correlated with shorter OS and RFS." (PMID 38563861, 2024). "Similar correlations were found for patients with gastric adenocarcinoma, whereas COMP expression was not prognostic in esophageal adenocarcinoma." (PMID 38563861, 2024). "In contrast, the presence of COMP in cancer cells or stroma was not prognostic in patients with esophageal adenocarcinoma." (PMID 38563861, 2024). "In patients with esophageal adenocarcinoma, stromal COMP expression was not correlated with any clinicopathological characteristic." (PMID 38563861, 2024). "Notably, COMP was prognostic in patients with gastric adenocarcinoma, but in contrast, it was not prognostic in patients with esophageal adenocarcinoma." (PMID 38563861, 2024).
gallstones (1 paper, 2024). Solid crystalline precipitates in the biliary tract, usually formed in the gallbladder, resulting in the condition of cholelithiasis. "The results indicated that AC004692.4, HECW1-IT1, SFRP4, and COMP were significantly higher expressed in gallstone samples, whereas LINC01564, SLC26A3, RP1-27K12.2, and GSTA2 were markedly lower expressed in gallstone samples compared to control samples." (PMID 38808330, 2024). "The upregulation of COMP and HECW1-IT1 is more commonly reported in cancer, and their regulatory roles in the mechanism of gallstone formation require further exploration." (PMID 38808330, 2024). "Furthermore, using RT-qPCR, we observed significant upregulation of AC004692.4, HECW1-IT1, SFRP4, and COMP, while LINC01564, SLC26A3, RP1-27K12.2, and GSTA2 exhibited marked downregulation in gallstone samples." (PMID 38808330, 2024).
gastric adenocarcinoma (1 paper, 2024). "In patients with gastric adenocarcinoma, COMP expression in both cancer cells and the stroma was associated with R-status (cancer cells p = 0.002; stroma p = 0.015), and COMP expression in cancer cells was associated with T-stage (p = 0.046)." (PMID 38563861, 2024). "In this study, we aimed to investigate the association of COMP expression with infiltrating immune cells and the organization of collagen fibers in esophageal and gastric adenocarcinoma." (PMID 38563861, 2024). "Future studies need to be conducted to clarify the prognostic role of COMP in patients with gastric adenocarcinoma." (PMID 38563861, 2024). "Cohorts with larger number of patients and the collection of serum samples are needed to clarify the role of COMP in patients with esophageal or gastric adenocarcinoma." (PMID 38563861, 2024). "COMP expression was evaluated in tissue microarrays representing primary tumors from 159 patients with chemo- and radiotherapy naïve esophageal and gastric adenocarcinoma and 67 matched samples of lymph node metastases using immunohistochemistry." (PMID 38563861, 2024). "When patients were stratified by primary tumor location, gastric adenocarcinoma patients with tumors with COMP expression in cancer cells had a median OS of 0.6 years, compared with 2.5 years for patients with tumors without COMP expression in cancer cells (p < 0.001)." (PMID 38563861, 2024).
gastric tumors (1 paper, 2024). "Interestingly, the correlation of COMP, and in general the wider family of thrombospondin proteins, with reduced infiltration of immune cells in gastric tumors has been predicted by a bioinformatic study." (PMID 38563861, 2024).
hypertriglyceridemia (1 paper, 2023). A laboratory test result indicating elevated triglyceride concentration in the blood. "Hypertriglyceridemia correlates with MetS-OA and increased serum COMP, a biomarker of cartilage breakdown." (PMID 36983885, 2023). "Further, in patients with early-stage disease, namely KL I and II knee OA with and without MetS, significant increases in serum COMP, a biomarker of cartilage degeneration, in MetS-OA was noted when compared to non-MetS OA, and positively correlated with hypertriglyceridemia." (PMID 36983885, 2023).
hypertrophic obstructive cardiomyopathy (1 paper, 2025). "The COMP gene was significantly expressed in distinct hypertrophic obstructive cardiomyopathy (HOCM) subtypes, highlighting its potential role in the molecular classification and pathogenic processes of HOCM." (PMID 40599543, 2025).
hyperuricemia (1 paper, 2014). An abnormally high level of uric acid. "Similar to type 1 collagen, COMP expression was significantly increased by hyperuricemia, P = 0.012." (PMID 25276832, 2014). "Hyperuricemia modified the expression pattern of extracellular matrix proteins, upregulating COL1 (P = 0.036) and COMP (P = 0.012) and downregulating HAS2 (P = 0.012)." (PMID 25276832, 2014).
Insulin resistance (1 paper, 2021). Increased resistance towards insulin, that is, diminished effectiveness of insulin in reducing blood glucose levels. "Key down-regulated genes (i.e., CREB5, SLC2A4, SREBF1, CYP1A1, CHARD and COMP) are related to insulin resistance, response to virus infection, AMPK signalling and ECM receptor interaction (Table A6)." (PMID 34830490, 2021).